STAT3 (signal transducer and activator of transcription 3)
Diseases named in the same sentence as STAT3 in open-access papers (continued):
Sharing a sentence is not in itself a finding about the gene and the disease.
tumor (continued). "STAT3 has been proposed as a therapeutic target for tumor cells as it is a downstream mediator of EGFR and IL6, both of which have been shown to be important in carcinogenesis and angiogenesis." (PMID 24404126, 2014). "For instance, TGF-β VEGF and IL-10 expressions are regulated by STAT3; furthermore, these proteins insure the continuance of STAT3 activation in immunosuppressive tumor microenvironment." (PMID 25333973, 2014). "In fact, some studies have suggested that STAT3 can act, paradoxically, as a tumor suppressor by participating in terminal differentiation and apoptosis." (PMID 24518612, 2014). "Results from these in vivo experiments clearly showed that while control cells initiated tumors in 100% (2×104) and 50% (1×104) of injection sites, STAT3-silenced cells initiated a tumor only in 19% and 6% of the cases, respectively." (PMID 25026286, 2014). "We suggest that the growth suppression engaged in normal cells and tissues by the recruitment of immune cells exposes the developing hyperplasia to OSM, which engages a JAK/STAT3-mediated tumor suppressive response." (PMID 24675570, 2014). "H-4073 mediated its anti-tumor effects by inhibiting JAK/STAT3, FAK, Akt and VEGF signaling pathways that play important roles in cell proliferation, migration, survival and angiogenesis." (PMID 24675768, 2014). "We further evaluated the effect of garcinol on constitutive p-STAT3 levels in HCC tumor tissues by immunohistochemical analysis and found that garcinol substantially inhibited the constitutive STAT3 activation in treated group as compared with control group." (PMID 24655440, 2014). "This is a reflection of previous studies indicating that inhibited STAT3 has been correlated with increased apoptosis in cancer cells, increased chemosensitivity, suppressed tumor growth, reduced invasiveness, and decreased angiogenesis." (PMID 24297508, 2014). "The expression of a key target of STAT3, miR-146b, which can be repressed by DNA methylation, is an important factor in understanding the biology and prognosis of a tumor." (PMID 24762632, 2014). "In cholangiocarcinoma, a high expression of the tumor suppressor gene regulator, gankyrin, favors tumor proliferation, invasion, and metastasis through activation of IL-6/STAT3 signaling pathway." (PMID 24901008, 2014). "In other words, STAT3 can be either oncogenic or tumor suppressive, depending on the use of different carcinogens." (PMID 24995504, 2014). "As a consequence, persistent activation of STAT3 mediates both the propagation of tumor-promoting inflammation and the suppression of anti-tumor immunity, thus forming a promising target to improve cancer therapy by modulating immune responses." (PMID 25149535, 2014). "Specifically, activated STAT3 promotes tumor cell proliferation, survival and invasion, and inhibits antitumor immune responses." (PMID 25013518, 2014). "Aberrant STAT3 activation is considered a molecular abnormality that supports the tumor phenotype and is detected with high frequency in hematological malignancies." (PMID 24520283, 2014). "Taken together, this study has demonstrated that STAT3 can function as a tumor suppressor as well as an oncoprotein, and the genetic background and/or coexisting biochemical defects of the cells play a key role in determining the functions of STAT3." (PMID 24995504, 2014). "The average tumor volume in mice from STAT3 KO group was 9 ± 2.9 mm3 and that in mice from PL treated group was 6 ± 2 mm3." (PMID 25216522, 2014). "These novel data suggest that the inclusion of a JAK2/STAT3 inhibitor such as CYT387 with paclitaxel has the potential of reducing the tumor volume further than that achieved by using chemotherapy alone." (PMID 24782986, 2014). "The Stat3 inhibitor, S3I-201, has been demonstrated to inhibit Stat3 dimerization and DNA-binding activity as well as inhibit cell proliferation and tumor growth." (PMID 25057499, 2014).
tumor (continued). "Similar to the signaling for IMQ-induced HIF-1α accumulation, we demonstrated that IMQ activated the PI3K/Akt and STAT3 pathways to enhance aerobic glycolysis in TLR7/8-negative tumor cells." (PMID 24658058, 2014). "The G-quartet ODN, which forms four-stranded G-quartet structures, uses another mechanism: it disrupts STAT3:STAT3 dimers and inhibits STAT3 binding to DNA, thereby inducing tumor cell apoptosis and tumor regression." (PMID 24743778, 2014). "Previous studies demonstrated that CuB suppressed the activation of STAT3, regulated STAT3 downstream genes and consequently inhibited tumor growth in several types of cancer." (PMID 25242136, 2014). "Tumor growth data showed that the 4T1 tumor mouse-derived B cells, which exhibited a higher level of STAT3, promoted tumor growth, while the JSI124-treated 4T1 mouse-derived B cells had a tumor suppressor function." (PMID 25013518, 2014). "JAK inhibitors AG490, WP1066, TG101209 and AZD1480 reduce the level of STAT3 phosphorylation, resulting in multiple anticancer effects such as decreased tumor growth, increased apoptosis, and reduced metastasis." (PMID 24743778, 2014). "Further study of the VEGF and STAT3 interactions will be required to better understand tumor escape and resistance patterns." (PMID 24518612, 2014). "IL-6 secretion can further increase STAT3 activation levels within tumor cells via an autocrine feedback loop." (PMID 25344679, 2014). "Recent evidence implicates STAT3 as key player for tumor immune surveillance as it both mediates the production of and response to inflammatory cytokines." (PMID 24473086, 2014). "Other small molecule inhibitors, including LLL12 and LLL3, suppress phosphorylation of STAT3 and inhibit STAT3 DNA binding, resulting in decreased viability of tumor cells and resultant apoptosis." (PMID 24518612, 2014). "Hepatocyte growth factor (HGF) and its receptor Met play a significant role in tumour progression partly through upregulation of Src, Stat3 activity, and VEGF expression." (PMID 25231728, 2014). "Together, these studies point to the potentially opposing role STAT3 can have on tumor growth by regulating these tumor suppressing transcription factors." (PMID 24743777, 2014). "GM-CSF-derived BMDCs from WT and STAT3 KO mice were pulsed for 14 hours with GL26 tumor lysate before being washed and administered as vaccines." (PMID 24806510, 2014). "Together these data show that STAT3 can both up regulate and down regulate the genes for cytokines that support immune function to suppress tumor growth." (PMID 24743777, 2014). "Studies showed that, during colitis-associated colonic tumorigenesis, IL-6 in the intestinal lamina propria enhances STAT3-dependent proliferation of tumor-initiating cells and protection of premalignant intestinal epithelial cells from apoptosis." (PMID 24757565, 2014). "We have previously demonstrated that a crosstalk initiated by endothelial cells enhances tumor cell survival and migration in vitro, and that endothelial cell-derived IL-6 induces phosphorylation of STAT3 in tumor cells." (PMID 24533454, 2014). "Further elucidation of mechanisms revealed that CXCR7 mediates tumor growth and metastasis by activating proinflammatory STAT3 signaling and angiogenic markers." (PMID 24886617, 2014). "Therapeutic agents blocking STAT3 are currently under development and predicted to block tumor progression in a variety of malignancies." (PMID 24473086, 2014). "Studies have shown that hyperactivation of STAT3 can contribute to tumorigenesis by inducing multiple tumour-promoting genes." (PMID 24757565, 2014). "As equally important, STAT3 regulates interactions between tumor cells and the microenvironment as well as immune cell activation." (PMID 24722453, 2014). "This protein has been suggested as a tumor suppressive protein by being a negative regulator of STAT3." (PMID 24498411, 2014).
tumor (continued). "It was found that the hepatocytes with STAT3 expression had a significantly less tumor formation induced by chronic carbon tetrachloride, as compared to hepatocytes with STAT3 knockout." (PMID 24995504, 2014). "STAT3 plays an important role in oncogenesis by up-regulating the transcription level of molecules promoting tumor cell survival, anti- apoptosis, cell cycle progression and angiogenesis." (PMID 25514838, 2014). "Constitutive expression of STAT3 alters gene-expression programs, inhibits expression of immune mediators and suppresses leukocyte infiltration into the tumor." (PMID 25594054, 2014). "A wide body of work spanning multiple solid tumor types, including PCa, have shown an indespensible and multifaceted role for STAT3 signaling in promoting tumor progression." (PMID 24722453, 2014). "Collectively, these studies demonstrated that endothelial cell-induced Akt and ERK phosphorylation in tumor cells induce a mutually compensatory effect, while the STAT3 pathway is activated independently." (PMID 24533454, 2014). "Our previous report showed that the number of MDSCs in tumor tissues significantly correlated with p-STAT3 expression in cancer cells." (PMID 25075523, 2014). "Myeloid-derived suppressor cells (MDSCs) function in immunosuppression and tumor development by induction of angiogenesis in a STAT3-dependent manner." (PMID 25075523, 2014). "Taken together, it appears that STAT3 up regulates many genes that support tumor metastasis through a variety of mechanisms." (PMID 24743777, 2014). "Studies that found STAT3 suppressed tumor immune surveillance found that STAT3 presence resulted in decreased levels of IFN-γ in murine macrophages." (PMID 24743777, 2014). "We believe that these findings are linked to the tumor suppressive effects of STAT1C in ESCC, as previous studies have shown that the relative proportions of STAT1 homodimers, STAT3 homodimers and STAT1:STAT3 heterodimers dictate the cell fate." (PMID 25355139, 2014). "Activators of STAT3 include tumor-secreted factors such as IL-10, IL6, EGF, FGF, and VEGF in addition to intracellular molecules such as Src kinase and breast tumor kinase." (PMID 24806510, 2014). "STAT3 appears to support tumor growth on multiple fronts of cell biology and in multiple stages of tumor development and progression." (PMID 24743777, 2014). "STAT3 can directly regulate the genes for multiple cytokines, which can lead to enhanced or suppressed tumor immune function." (PMID 24743777, 2014). "As a transcription factor and oncogene, STAT3 promotes the expression of genes which allow tumor cells to proliferate, migrate and evade apoptosis." (PMID 24806510, 2014). "Although it is known that the constitutively-active form of STAT3 plays key roles in tumorigenesis and tumor progression, the molecular mechanism by which the STAT3 is activated in hypoxic cancer cells is poorly understood." (PMID 25594014, 2014). "One possible explanation for this effect is that the STAT1/STAT3 heterodimers have a distinct role in tumor angiogenesis independent from the role of STAT1 or STAT3 homodimers, but further work is necessary to elucidate this effect." (PMID 24404126, 2014). "In this study we used a conditional Stat3 knockout mouse model to investigate the consequences of Stat3 deletion for BCR/ABLp185+-driven tumor growth." (PMID 24473086, 2014). "Inflammatory mediators like Hmgb1, IL-23, and IL17 can promote tumor growth by activating IL-6/STAT3 pathway in a mouse model of melanoma." (PMID 24901008, 2014). "This phenomenon depends on hypoxia-induced VEGF-A since VEGF-A neutralization restores the susceptibility of tumor cells to CTL lysis and also on STAT3 activation." (PMID 24765614, 2014). "In another study, persistent STAT3 activation was detected in distant organs such as the lung before tumor cell arrival." (PMID 25566502, 2014).
tumor (continued). "Accumulating evidences have shown a positive correlation between the inhibition of STAT-3 signaling and suppression of tumor cell proliferation." (PMID 25296162, 2014). "STAT3 induction of angiogenesis and proteases that support angiogenesis and cell invasion together make a lethal combination in tumor biology." (PMID 24743777, 2014). "We have characterized a novel immunosuppressant, which shows potential anti-tumor effects on CC via p-STAT3 inhibition." (PMID 25344679, 2014). "Second, IMQ induced ROS production, thereby increasing HIF-1α expression at the transcriptional and translational levels via the PI3K/Akt and STAT3 pathways, which triggered aerobic glycolysis in tumor cells." (PMID 24658058, 2014). "The induction of anti-tumor immune responses by STAT3 null DCs was also evaluated in a therapeutic treatment model in which DCs were administered post tumor cell implant." (PMID 24806510, 2014). "Constitutively activated or overexpressed STAT3 can be detected in multiple tumor-derived cell lines as well as samples from common malignant tumors, such as colon, skin, gastric, breast, and lung." (PMID 25126546, 2014). "Given the difference in the timing of activation, it is probable that Wnt and STAT3 signalling confer different selective advantages to tumour cells." (PMID 25348333, 2014). "We found that STAT3 is required to attract NK cells to the tumor, which restrict and limit tumor growth." (PMID 24473086, 2014). "This was supported by the inverse correlation between E-cadherin and IL-6 expression, positive correlation between IL-6 and vimentin mRNA expression and between STAT3 phosphorylation and IL-6 expression in tumor tissues." (PMID 24789104, 2014). "Activation of STAT3 downstream of cell surface receptors for cytokines and growth factors, by oncogenes or by chemical carcinogens in the microenvironment of many tumor types drives their transformation, survival, proliferation, invasion and dissemination." (PMID 24722453, 2014). "Tumor suppressive signaling can often be observed in normal cells following prolonged STAT3 activation." (PMID 24675570, 2014). "Constitutive activation of STAT proteins, notably of STAT3, is detected in many human tumor cells and cells transformed by oncoproteins." (PMID 25365510, 2014). "Previous study identified Stat3 as a critical molecule in myeloid derived suppressor cells (MDSCs) accumulation in tumor-bearing mice." (PMID 24416452, 2014). "Constitutive activation of the Stat3 signaling pathway has been observed in tumor cells as well as infiltrating cells, including TAMs." (PMID 24723924, 2014). "These two TFs are directly involved in pancreatic tumorigenesis and proliferation, and are thought to play opposite roles - while STAT1 promotes apoptosis, STAT3 is essential for the proliferation and survival of tumour cells." (PMID 25521701, 2014). "Fascin expression positively correlated with the expression of both LMP1 and the phosphorylated transcription factor signal transducer and activator of transcription 3 (STAT3), as well as with the proliferation index of the tumor cells." (PMID 25105941, 2014). "Another transgenic mice model, K5.CreERT2, with a tamoxifen inducible Cre gene under the control of K5 promoter, was used to study STAT3 effect on tumor transformation in a temporally controlled and inducible pattern." (PMID 24743778, 2014). "To exclude that we omitted tumor appearances due to the decreased proliferation rate of STAT3-silenced cells, we performed long tumor follow-up (10 weeks)." (PMID 25026286, 2014). "STAT3 is activated through the IL-6 Pathway, which was also among the top 10 canonical pathways regulated by FoxO in response to tumor burden." (PMID 25539728, 2014). "Lastly, STAT3 has a significant impact on tumor immune function through its role in the development of Th17 T helper cells." (PMID 24743777, 2014).
tumor (continued). "One such NF-κB regulated gene is IL-6, which is produced in an autocrine fashion by many tumor cells and leads to STAT3 phosphorylation via Jak family kinases." (PMID 24762632, 2014). "Whereas the importance of STAT5 as tumor promoter is beyond doubt, the role of STAT3 in hematological cancers is less well understood." (PMID 24473086, 2014). "STAT3 achieves promoting tumor immune evasion by directly upregulating expression of multiple cytokines that suppress immune function." (PMID 24743777, 2014). "Considering that the active form of STAT3 (pSTAT3) is transported into the nucleus to be functional, cases that exhibited nuclear staining in more than 30% of tumor cells were interpreted as being positive for pSTAT3 expression." (PMID 25472725, 2014). "IDO-positive tumor cells and tissues showed basal phosphorylation and acetylation of STAT3 as evidenced by western blotting and immunoprecipitation." (PMID 24657910, 2014). "Due to the involvement of STAT3 in key regulatory pathways in tumor cells, several investigators have examined the efficacy of inhibiting STAT3 as anti-cancer therapy." (PMID 24404126, 2014). "STAT3 also recruits and promotes the proliferation of T regulatory cells (Tregs), which suppress effector lymphocyte activity within the tumor microenvironment." (PMID 24518612, 2014). "STAT3 inhibition has been found to induce cell cycle arrest and apoptosis in STAT3-positive tumor cells." (PMID 24505404, 2014). "Two key control elements, NFκB and STAT3 were shown to regulate coordinately the production of multiple tumor-derived immunosuppressive molecules and play a pivotal role in tumor cell immune suppression." (PMID 24995006, 2014). "In the contrary, Stat3 is required for gap junctional communication and the maintenance of Cx43 levels, both in normal epithelial cells and in certain tumor lines that retain GJIC." (PMID 24670366, 2014). "Considering MMPs promote cancer cell invasion, metastasis, and angiogenesis, it would seem that STAT3 upregulation of an endogenous inhibitor to MMPs is another example of STAT3 showing both oncogenic and tumor suppressor functions." (PMID 24743777, 2014). "Several dietary antioxidants are recognized to block tumour development by targeting the STAT3 signaling network." (PMID 25296162, 2014). "In this manner, STAT3 can regulate a pro-carcinogenic inflammatory microenvironment and tumor immunity." (PMID 24662939, 2014). "Our data show that sorafenib-YC-1 combination is a novel potent therapeutic agent that can target the STAT3 signaling pathway to inhibit HCC tumor growth." (PMID 24418169, 2014). "In studies identifying STAT3 as a tumor immune suppressor, one of the observations was decreased levels of IL-6 with increased STAT3 expression in NIH-3T3 cells and murine macrophages." (PMID 24743777, 2014). "Aberrantly active STAT3 contributes to oncogenesis by preventing apoptosis, inducing cell proliferation and suppressing anti-tumor immune responses." (PMID 25261365, 2014). "Acetylation of STAT3 is elevated in tumors and contributes towards tumor progression by inducing DNA methylation at the promoters of tumor suppressor genes." (PMID 24655440, 2014). "Constitutive STAT3 activation relieves tumor cells from their dependence on cytokines and growth factors—thereby allowing continuous cell cycle progression and proliferation." (PMID 24473086, 2014). "We propose that early breast hyperplasia engages microenvironmental responses from infiltrating immune cells, or other stromal components that lead to persistent JAK/STAT3-signaling and a tumor suppressive arrest." (PMID 24675570, 2014). "It is well established that activation of the STAT3 signaling pathway promotes tumor growth and expression of pro-angiogenic factors." (PMID 24533454, 2014). "As a transcription factor, STAT3 mediates the expression of genes such as Cyclin-D, Bcl-xl, and survivin, which promote the growth and survival of individual tumor cells." (PMID 24806510, 2014).